RECQL4 (RecQ like helicase 4)
Diseases named in the same sentence as RECQL4 in open-access papers (continued):
Sharing a sentence is not in itself a finding about the gene and the disease.
Hoyeraal-Hreidarsson syndrome (1 paper, 2019). Hoyeraal-Hreidarsson syndrome (HHS) is a very rare X-linked recessive disorder considered to be a severe variant of dyskeratosis congenita characterized by intrauterine growth retardation, microcephaly, cerebellar hypoplasia, progressive combined immune deficiency and aplastic anemia. "RECQL4 (Rothmund-Thomsun syndrome) and RTEL1 (Hoyeraal-Hreidarsson Syndrome), deficiencies impart increased risks of cancer cancer, autoimmunity and premature ageing." (PMID 31287417, 2019).
hypospadias (1 paper, 2019). Hypospadias is the displacement of the urethral meatus on the ventrum of the penis. "Patient 3 presented two variants in two genes: GLI2 (associated to gonadal/genital anomalies) and RECQL4 (associated to syndromic hypospadias)." (PMID 31555317, 2019). "Patient 2 carried one variant in RECQL4, associated with syndromic hypospadias." (PMID 31555317, 2019).
metastasis (1 paper, 2021). The spread or migration of cancer cells from one part of the body (where they first appeared) to another. "RECQL4 expression strongly correlated with tumor differentiation (P = 0.011), depth of invasion (P = 0.033), and lymph node metastasis (P = 0.048)." (PMID 33628589, 2021).
multiple myeloma (1 paper, 2018). "The RECQL4 frameshift mutation c.2636del was found in patient HPC455, who has also multiple myeloma (B2 criterion)." (PMID 29659569, 2018).
neurofibroma (1 paper, 2025). An intraneural or extraneural neoplasm arising from nerve tissues and neural sheaths. "RECQL4 expression was significantly higher in neurofibromas (median H-score: 160) compared with MPNST (median H-score: 97.5, Wilcoxon rank-sum test, W = 1590, P < 0.0001)." (PMID 41317405, 2025). "All cases with RECQL4 alterations in this cohort were neurofibromas; there were no RECQL4 alterations in cases of MPNST." (PMID 41317405, 2025).
oral cancer (1 paper, 2020). "Consistently, amplification of RECQL4 is related to the development of breast and oral cancer." (PMID 33014878, 2020).
orofacial cleft (1 paper, 2022). A disorder of facial skeleton that is characterized by cleft lip and/or cleft palate that result in feeding, speech and hearing problems caused by failures during development. "Mouse knockouts of Acan,Dhrs3, Kmt2d, Recql4, Shh and Tp63 showed orofacial cleft phenotypes." (PMID 35817949, 2022).
ovarian tumors (1 paper, 2024). "Except for ATAD2, expression of other genes (ASF1B, CCNE1, CDC20, CDCA8, RECQL4, RNASEH2A, and SMC4) was upregulated in ovarian tumors compared to non-cancerous tissue." (PMID 39199556, 2024).
pancreatic insufficiency (1 paper, 2015). "In the literature, two articles have described pancreatic insufficiency with fatty pancreatic degeneration in RTS-like individuals without any mutation in the RECQL4 gene." (PMID 26471370, 2015).
pediatric cancer (1 paper, 2020).
prostate tumor (1 paper, 2013). "On the contrary, elevated RecQL4 expression has also been reported in human sporadic osteosarcoma and prostate tumor samples." (PMID 23894508, 2013). "We observed that RecQL4 is most highly expressed in metastatic breast tumors, together with our previous findings in prostate tumors suggests that elevated expression of RecQL4 is potentially significant for metastatic progression of the disease." (PMID 23894508, 2013).
radial aplasia (1 paper, 2019). "Bi-allelic RECQL4 mutations are associated with radial aplasia and hypoplasia syndromes, and we considered further follow up to be indicated." (PMID 30712880, 2019).
sarcoma (1 paper, 2020). A usually aggressive malignant neoplasm of the soft tissue or bone.
skin cancer (1 paper, 2014). "For example, BLM, WRN, and RECQL4 are mutated in Bloom, Werner, and Rothmund-Thomson genomic instability syndromes, respectively, and XPB and XPD are mutated in Xeroderma Pigmentosum, characterized by high risk of skin cancer." (PMID 25238049, 2014).
triple-negative breast carcinoma (1 paper, 2022). An invasive breast carcinoma which is negative for expression of estrogen receptor (ER), progesterone receptor (PR), and human epidermal growth factor receptor 2 (HER2). "Furthermore, recent studies suggest that human RECQL4 also has a role in crosslink repair since RECQL4 shRNA knockdown leads to cisplatin sensitivity in a triple-negative breast cancer (TNBC) cell line." (PMID 36126066, 2022).
cancer (115 papers, 2006 to 2026). A tumor composed of atypical neoplastic, often pleomorphic cells that invade other tissues. "Loss of RECQL4 helicase activity predisposes patients to premature aging and cancers in Rothmund-Thompson, RAPADLINO, and Baller-Gerold Syndromes26." (PMID 40196015, 2025). "Although recent work by others has correlated loss or gain of RECQL4 expression with cancer susceptibility, the reciprocal interplay of RECQL4‐driven signalling pathways with signatures driving immunotherapy efficacy is yet to be elucidated." (PMID 39812592, 2025). "The detection of clinically relevant RECQL4 mutations demonstrated the dual roles of RECQL4 helicases: first in maintaining the genome integrity, secondly in DNA repair which determines responses to therapeutic drugs in the case of cancer." (PMID 41419455, 2025). "RTS type 2, caused by pathogenic variants in RECQL4, is characterized by poikiloderma, congenital bone defects, and an increased risk of cancer." (PMID 41333505, 2025). "In cancer cells deficient in HR, both a PolQ inhibitor and RECQL4 knockdown effectively eliminated these HR-deficient cells." (PMID 39870799, 2025). "Our pan-cancer database screen supports that high RECQL4 levels are associated with genomic instability, metastasis, and poor outcomes in patients with elevated RECQL4 mRNA in tumors and with RECQL4 gene amplification." (PMID 40196015, 2025). "All these three syndromes are correlated to cancer, particularly Rothmund–Thomson syndrome patients with RECQL4 mutations shown an increased risk of osteosarcoma." (PMID 38509102, 2024). "Biallelic mutations in these RecQ homologs, WRN, BLM, and RECQL4, have been previously reported to be associated with rare human genetic diseases characterized by chromosomal instability and cancer susceptibility." (PMID 37180972, 2023). "RECQL4 is associated with various DNA repair pathways and contributes to the pathogenicity of various human cancers." (PMID 37516854, 2023). "Specifically, RECQ helicases, including BLM, WRN, and RECQL4, are associated with various hereditary disorders characterized by cancer." (PMID 37415147, 2023). "A recent study examined the prevalence of cancer risk in patients carrying monoallelic pathogenic variants in the RECQL4 gene." (PMID 35782872, 2022). "Although RECQL4 mutations lead to disease, RECQL4 overexpression is also observed in cancer, including breast and prostate." (PMID 36126066, 2022). "In this review, we focus on the roles of RecQ helicases, particularly on the cancer-associated BLM, WRN, and RECQL4, and discuss their potential as targets for cancer treatment." (PMID 35267530, 2022). "Mutations in three of the five human RecQ helicases (WRN, BLM and RecQL4) are yet known to result in premature aging syndromes characterized by increased cancer predisposition: Werner, Bloom and Rothmund-Thomson." (PMID 35935726, 2022). "Biallelic, loss-of-function germline pathogenic variants in three of them, BLM, WRN, and RECQL4, have been linked to rare cancer-predisposing syndromes." (PMID 35782872, 2022). "Here we used the budding yeast homolog of RECQL4, Hrq1, and discovered that overexpression of Hrq1 protein levels result in increased recombination and mutations, both cancer hallmarks." (PMID 36126066, 2022). "Strikingly, biallelic mutations in 3 of 5 of these RecQ homologs — WRN, BLM, and RECQL4 — have been associated with rare genetic disorders in humans, characterized by chromosomal instability and cancer predisposition." (PMID 35025765, 2022). "Among these five, mutations in BLM, WRN, and RECQL4 are associated with premature aging and a higher risk of developing cancers." (PMID 35267530, 2022). "Biallelic germline mutations in BLM, WRN, and RECQL4 have been linked to rare cancer-predisposing syndromes." (PMID 35782872, 2022). "Recent studies have shown that RECQL4 is overexpressed in most cancers and is associated with clinical outcomes." (PMID 36544763, 2022).
cancer (continued). "Although RECQL4 dysfunction is associated with hereditable diseases, recent studies have shown that overexpression of RECQL4 is linked to multiple cancer types such as breast, hepatic, gastric, and prostate." (PMID 36126066, 2022). "have revealed that cancer-related RECQL4 mutations stimulate abnormally high levels of mitochondrial DNA synthesis, resulting in disorders in mitochondrial metabolism." (PMID 35572523, 2022). "Overall, our study uncovers a role for Hrq1/RECQL4 in DNA intrastrand crosslink repair and provides further insight how misregulation of RECQL4 can promote genomic instability, a cancer hallmark." (PMID 36126066, 2022). "Consistent with these diverse roles, mutations in RECQL4 are associated with three distinct genetic diseases, which are characterized by developmental defects and/or cancer predisposition." (PMID 34946868, 2021). "BLM, WRN, and RECQL4 are associated with genetic disorders characterized by chromosomal instability, premature aging, and increased susceptibility to cancer." (PMID 33824465, 2021). "Mutations in human RecQ helicases BLM, WRN and RecQL4 cause incurable disorders characterized by genome instability, increased cancer predisposition and premature adult-onset aging." (PMID 32085395, 2020). "Mutations in genes coding for BLM, WRN and RECQL4 helicases are associated with recessive autosomal syndromes characterized by chromosomal instability, premature aging and predisposition to cancer." (PMID 33050631, 2020). "RECQL is one of the five RECQ genes, three of which (BLM, WRN and RECQL4) have been implicated in genetic disorders with increased cancer risk." (PMID 30610487, 2019). "RECQL4, which is mutated in the Rothmund–Thomson syndrome characterized by premature aging and cancer susceptibility, is a microtubule-associated protein required for mitotic chromosome alignment." (PMID 30718377, 2019). "Mutations in RECQL4 cause the Rothmund–Thomson syndrome, characterized by premature aging and susceptibility to certain cancers." (PMID 30718377, 2019). "A hypomorphic mutation deleting a single exon leads to growth retardation and developmental abnormalities, whereas exon deletions causing truncation of the C-terminal part of RECQL4 result in aneuploidy and cancer predisposition in mice." (PMID 30718377, 2019). "Cells of patients suffering from the disease display severe chromosomal instability consistent with observations that hypomorphic RECQL4 variants in mice result in aneuploidy and cancer predisposition." (PMID 30718377, 2019). "Out of 35 RECQL4-mutated patients, 34 carried at least one pathogenic variant affecting the helicase domain, confirming the association between deleterious mutations in the RECQL4 gene and cancer predisposition first assessed by Wang in 2003." (PMID 29642415, 2018). "All three RECQL4-associated diseases are clinically characterized by growth delay, bone alterations and cancer predisposition, and the underlying biallelic pathogenic variants exert their effect by a loss-of-function mechanism." (PMID 29642415, 2018). "The identification and characterization of RECQL4 mutations is relevant in order to assess the patients' cancer risk, to avoid extensive and inconclusive clinical evaluations and to clarify the recurrence risk in the families." (PMID 27247962, 2016). "Functional autosomal recessive loss of BLM, WRN and RECQL4, results in hereditary human syndromes characterized by cancer predisposition and premature aging (Bloom's, Werner's, and Rothmund-Thomson's syndromes, respectively)." (PMID 27764811, 2016). "Mutations in three of which including BLM, WRN and RecQL4 have been linked to distinct human disorders with common characteristics of premature aging and cancer predisposition." (PMID 23894508, 2013).
cancer (continued). "Three of the human RecQ helicase disorders with mutations in WRN, BLM and RecQL4 helicases exhibit premature aging and cancer susceptibility owing to perturbations in DNA replication, transcription, recombination and repair." (PMID 23894508, 2013). "Of the five human RecQ helicases, three (WRN, BLM and RECQL4) are associated with diseases involving segmental premature aging and cancer predisposition." (PMID 23238538, 2012). "Mice with deletion of the Recql4 helicase domain also show congenital skeletal defects, a distinctive skin abnormality and increased cancer susceptibility in a sensitised genetic background." (PMID 20113479, 2010). "We found that this pathway requires RecQL4, a protein facilitating DNA repair and mitochondrial maintenance whose disruption can lead to several devastating human diseases associated with premature aging and cancer predisposition." (PMID 40319014, 2025). "Furthermore, mutations in BLM, WRN, and RECQL4 are associated with Bloom, Werner, and Rothmund‐Thomson syndromes, respectively, all of which present genome instability and cancer predisposition." (PMID 39462683, 2025). "To test our hypothesis that RECQL4 upregulation may be associated with cancer progression per se, we analysed RECQL4 expression comparing tumour samples to adjacent normal tissue in several tumour entities from the TCGA database." (PMID 39812592, 2025). "These factors coupled with RECQL4’s known functions in the nucleus altogether may contribute to the cancer predisposition phenotype seen in patients with RTS." (PMID 37495109, 2023). "RECQL4 mutations are associated with developmental defects and cancer." (PMID 36126066, 2022). "Rather, it may be involved in protein stability, and mutations may lead to cancers and specific RECQL4-associated syndromes." (PMID 35782872, 2022). "Thus, in the case of biallelic loss of gene function, evidence suggests an association of RECQL4 with cancer predisposition." (PMID 33541411, 2021). "The impact of a heterozygous RECQL4 mutation on cancer predisposition unknown, particularly in the context of simultaneously inherited DNA damage and repair gene mutations like BAP1 and/or MSH6." (PMID 33541411, 2021). "For instance, defects in pol ε, PCNA and RECQL4 lead to increased risk for cancer." (PMID 33477564, 2021). "What is particularly striking is that these symptoms overlap with diseases affecting replication origin licensing factors (MGS and skeletal anomalies), firing factors (NKD and immunodeficiency) and repair factors (RECQL4 and cancer predisposition/skin phenotypes)." (PMID 33477564, 2021). "Loss of RECQL4 function is associated with chromosomal instability, which is a driver of cancer." (PMID 34946868, 2021). "We have characterized the causative RECQL4 genetic lesions and have explored their pathogenic effect by in silico predictions and transcripts analyses to address mutation-phenotype correlation, especially in relation to cancer development." (PMID 29642415, 2018). "The absence of the cataract makes the distinction between the two clinical variants of RTS: the form with poikiloderma and ocular defects, named RTSI, and poikiloderma, skeleton defects, predisposition to cancer and RECQL4 mutations, named RTSII, which accounts for approximately 66% of RTS patients." (PMID 28039508, 2017). "RECQL4 is one of five members of the human RecQ helicase family, and is implicated in three syndromes displaying accelerating aging, developmental abnormalities and a predisposition to cancer." (PMID 23238538, 2012). "In vivo, chromosomal instability may drive neoplastic transformation of cancer stem/progenitor cells that are especially sensitive to the effect of RECQL4 mutations." (PMID 20113479, 2010). "In keeping with these findings, an increased risk of cancer may be predicted for patients with RECQL4 mutations belonging to all RECQL4 syndromes." (PMID 20113479, 2010). "Defects of WRN, BLM and RECQL4 may increase cancer predisposition in humans." (PMID 31897211, 2020).